PRMT1 (protein arginine methyltransferase 1)
Diseases named in the same sentence as PRMT1 in open-access papers (continued):
Sharing a sentence is not in itself a finding about the gene and the disease.
cancer (continued). "To study the biological roles of PRMT1 and c-Fos, we analyzed PRMT1 expression data for a variety of cancers obtained from The Cancer Genome Atlas (TCGA) by employing TIMER." (PMID 37564212, 2023). "PRMT1 expression is critical in maintaining cell cycle processes in many types of cancer, and its depletion significantly reduces the number of cells in the S phase of the cell cycle." (PMID 36637997, 2023). "GSK3368715, a PRMT1 inhibitor, exerts antitumor activity in vitro and in vivo in multiple cancer types with splicing alteration activity of exon usage." (PMID 37342192, 2023). "Given the critical role of PRMT1 in cGAS-dependent DNA sensing signaling and immune suppression in human and mouse tumor cells, we next examined the potential of PRMT1 as a target of cancer immunotherapy." (PMID 37193698, 2023). "A growing number of studies indicated that ADMA modification by PRMT1 participates in various biological processes, including tumorigenesis and cancer metastasis." (PMID 37737256, 2023). "A recent study in cancer cells demonstrated that PRMT1 directly interacts with HSP70 and catalyzes its methylation, which is then crucial for its binding and stabilization of mRNA." (PMID 36197469, 2022). "Later, a number of chemically symmetrical diamidine compounds as PRMT1 inhibitors with activities against cancer cells were reported, including stilbamidine and furamidine (DB75)." (PMID 35755248, 2022). "Under the condition of MICU1 methylation by PRMT1 in aging or cancer, UCP2 that binds to methylated MICU1 destabilizes CJ, disrupts SMPGs, and facilitates fast Ca2+ uptake via the CM." (PMID 35778442, 2022). "These and other studies have identified PRMTs, specifically PRMT1, as a key contributor to the proliferation of cancers through various mechanisms including epigenetic-mediated gene expression." (PMID 35764172, 2022). "Previous studies on arginine methyltransferases in cancers have mostly focused on PRMT1, CARM1, and PRMT5." (PMID 36199122, 2022). "Overexpression of PRMT1 has been demonstrated in many types of human cancers, and PRMT1 participates in certain cancers via its posttranslational modification functions." (PMID 36151091, 2022). "The highest expression of PRMT1 mRNA in TNBC was confirmed in the publicly available database—the cancer genome atlas (TCGA) cohort." (PMID 35053470, 2022). "PRMT1 inhibitors are being developed to treat various cancers 67-69, it is necessary to evaluate the potential side effects of PRMT1 inhibitor treatments on hepatic lipid metabolism and liver damages." (PMID 35401831, 2022). "Further studies have also identified overexpression of PRMT1 in some cancers, including leukemia, prostate, esophageal, lung, bladder, and breast compared to normal cells leading to increased protein levels and promoting cell proliferation." (PMID 35764172, 2022). "Consistently, previous reports indicate that EIF5A and PRMT1 promote cell proliferation in the case of several human cancers." (PMID 35450295, 2022). "To explore the relationship between PRMT2/4-mediated BRD4 methylation and DDR, we induced DNA damage using a topoisomerase II inhibitor, etoposide, which has been used in PRMT1/5-relevant studies and is widely used for cancer treatment." (PMID 36475791, 2022). "It has been found that expression of certain PRMT genes is altered in some cancer types such as PRMT1 and CARM1 overexpressed in breast and prostate cancers or PRMT5 and PRMT6 overexpressed in lung and blood cancers." (PMID 36358861, 2022). "Especially cancer cells show a clear increase in UCP2 but also PRMT1 expression and both proteins when highly expressed are prognostic markers for lung carcinoma patients." (PMID 35778442, 2022). "MICU1 has been shown to be methylated by protein arginine methyltransferase 1 (PRMT1) in cancer cells, yielding decreased Ca2+ sensitivity and reduced Ca2+ entry." (PMID 35743109, 2022).
cancer (continued). "In LSK-derived MLL-cancer stem cells, the PRMT1 function is coregulated by β-catenin and Hoxa9; by mediating similar signaling pathways as β-catenin and Hoxa9, PRMT1 is directly involved in leukemic cell self-renewal." (PMID 36358861, 2022). "Many experimental studies have shown that PRMT1 is overexpression or has an shear state in many cancer types." (PMID 36713412, 2022). "Targeting PRMT1 has been shown to generate neoantigens in cancer cells, accounting for its high efficacy in cancer treatment in combination with immune checkpoint blockers." (PMID 36152748, 2022). "It has been reported that the PRMT1 inhibitor GSK715 is in a phase I clinical trial of cancer treatment." (PMID 34775498, 2021). "The reactions catalyzed by PRMT1 are crucial for maintaining cellular health, and dysregulated PRMT1 contributes to the pathology of several cancers." (PMID 34688662, 2021). "Taken together, these data revealed that PRMT1 inhibitor blocks cancer cell growth and induces cellular senescence and death." (PMID 34440533, 2021). "It has been reported that many PRMT1 inhibitors can attenuate cancer cell growth in vitro and in vivo." (PMID 34775498, 2021). "As described for other cancers, PRMT1 expression is significantly increased in lung cancer tissue compared to non-neoplastic ones though very little data are available in the literature to explain its role in lung carcinogenesis." (PMID 34833023, 2021). "Dysregulation of PRMT1 expression has been reported in several other types of cancers, albeit the molecular mechanisms that drive the initiation and progression of these cancers remain incompletely understood." (PMID 34833023, 2021). "Its key role in cancer initiation and progression makes PRMT1 an interesting target for the development of new anti-cancer therapeutic strategies." (PMID 34833023, 2021). "For example, CBX7 positively regulated E-cadherin expression by inhibiting HDAC2 and PRMT1 activity on the E-cadherin promoter, and thereby suppressed cancer progression." (PMID 34035231, 2021). "Recently, many reports have demonstrated that the ectopic expression of PRMT1 in a variety of cancers plays a key role in cancer tumorigenesis and metastasis." (PMID 34775498, 2021). "These provide the foundation for clinical evaluation of PRMT5 (four clinical trials) and PRMT1 (one clinical trial) in cancer therapy." (PMID 32743345, 2020). "PRMT1 has been identified as a key common downstream mediator for β-catenin/Hoxa9 functions in MLL in the context of cancer stem cells." (PMID 32517078, 2020). "PRMT1 has functions in oxidative stress, inflammation and cancers, and modulates diverse diseases; consequently, numerous trials to develop PRMT1 inhibitors have been attempted." (PMID 32357521, 2020). "Very recently, the involvement of Prmt1 in the apoptosis of tumor cells has been demonstrated, although with opposite roles in different types of cancer." (PMID 32231994, 2020). "The PRMT1 enzyme depletion has been shown to induce cell cycle arrest and reduce cancer cell proliferation, while an overexpression of one of the PRMT1 variants has been shown to reduce apoptosis." (PMID 32932854, 2020). "In particular, the expression of PRMT1 and ZEB1 in ccRCC, as well as low-nuclear tumor grade and low-tumor stage were significantly associated with better cancer-specific survival (p = 0.029, p = 0.009, p < 0.001 and p < 0.001, respectively)." (PMID 31655611, 2019). "Early experiments showed that PRMT1 is required for the neuronal differentiation potential of the cancer cells derived from neural crest cells." (PMID 30741995, 2019). "Recently it was reported that INCENP is mono-methylated on Arg887 by PRMT1, and that this promotes mitosis of cancer cells." (PMID 31320618, 2019). "Taken together, we conclude that PRMT5 and PRMT1 truly affect apoptosis induced by anti-cancer drugs doxorubicin and pemetrexed in NSCLC cells." (PMID 30736843, 2019).
cancer (continued). "PRMT1 and ZEB1 expression were associated with better cancer-specific survival in patients with ccRCC (p = 0.029; p = 0.009, respectively)." (PMID 31655611, 2019). "In line with this assumption, cancer cells depleted from PRMT1 and UCP2 showed an increased vulnerability and exhibited a largely decreased cell viability and proliferation." (PMID 29113301, 2017). "Methylation by protein arginine methyl transferase 1 (PRMT1) desensitizes the mitochondrial Ca2+ uptake machinery and reduces mitochondrial Ca2+ accumulation in cancer cells." (PMID 29113301, 2017). "Based on our previous work, we assume that this positive impact of UCP2 and PRMT1 on cancer cell viability and proliferation is due to a more efficient mitochondrial respiration." (PMID 29113301, 2017). "In this study, we considered the recent reports on the functional interaction of UCP2 and PRMT1 and investigated the importance of this relation on cancer cell's viability, proliferation and patient's survival." (PMID 29113301, 2017). "Nevertheless, to ensure sufficient mitochondrial Ca2+ uptake, the uncoupling protein 2 (UCP2) is able to normalize mitochondrial Ca2+ uptake in case of PRMT1-driven methylation of MICU1 in cancer cells." (PMID 29113301, 2017). "In previous reports, PRMT1 was significantly elevated in several types of cancer and played an important role in cancer progression." (PMID 29383172, 2017). "We showed that the EMT program induced by PRMT1 endowed the human mammary epithelial cells with cancer stem cell properties." (PMID 26813495, 2016). "Protein arginine methylation has been implicated in signal transduction, gene transcription, DNA repair and mRNA splicing, among other functions and aberrant expression of PRMT1 has been found in various types of cancer." (PMID 27571165, 2016). "Significantly, our work suggests that PRMT1 is a new epigenetic regulator in generation of cancer sternness, and this finding provides a basis for the development of therapeutic strategy for highly aggressive and malignant breast cancers." (PMID 26813495, 2016). "The current establishment of an in vivo preclinical model provides a strong rationale and platform to evaluate and develop more specific Prmt1 inhibitors in the future for targeted cancer therapy." (PMID 26766589, 2016). "Our current studies provide the key in vivo experimental evidence demonstrating the requirement of KDM4C for cancer development and its functional crosstalk with PRMT1 in the establishment of histone codes for transcriptional deregulation in AML." (PMID 26766589, 2016). "Since, EMT is increasingly recognized as an essential event in cancer progression and metastasis, we evaluated first the role of PRMT1 on EMT." (PMID 25847239, 2015). "Knockdown of PRMT1 as well as overexpression of methylation-inactive INCENP attenuated the AURKB activity in cancer cells, and resulted in abnormal chromosomal alignment and segregation." (PMID 26460953, 2015). "Our findings identify a new role for PRMT1 in the cytoplasm that is required for cancer cell survival." (PMID 26267306, 2015). "Protein arginine methyl transferase 1 (PRMT1) was shown to be up-regulated in cancers and important for cancer cell proliferation." (PMID 25847239, 2015). "Since our data revealed that PRMT1-mediated INCENP methylation is critical for the activation of AURKB, we then examined the effect of PRMT1 knockdown on the cell division of cancer cells." (PMID 26460953, 2015). "The data indicate that INCENP methylation at R887 by PRMT1 is critical for the growth of cancer cells." (PMID 26460953, 2015). "PRMT1 expression was shown to be up-regulated in cancers and important for cancer cell proliferation." (PMID 25847239, 2015). "Both SRSF1 and PRMT1 were over-expressed in ND samples, and were reduced to normal levels upon CR, which is supported by reports that SRSF1 and PRMT1 are highly expressed in many cancers." (PMID 22839530, 2012).
cancer (continued). "Studies on the physiological function of PRMT1 in normal colon will shed more light into the role of this enzyme in cancer as well as other diseases." (PMID 19078953, 2008). "It would be interesting to additionally investigate the relationship between PRMT1 and BRCA2, but all current evidence already suggests that PRMT1 inhibition may be an appealing therapeutic approach in cancer." (PMID 40001488, 2025). "This post‐translational modification promotes PRMT1‐vimentin interaction and subsequent asymmetric dimethylation (aDMA) of vimentin at arginine (R64), driving cytoskeletal remodeling and metastatic competence in cancer cells." (PMID 40884268, 2025). "Previous studies have highlighted the high expression and cancer-promoting role of PRMT1 in cancer." (PMID 39890802, 2025). "Given the effectiveness of targeting PRMT1 in reducing persistence in STAT1-high cancer cells, we reasoned that genetic alterations in the STAT1 pathway could provide clues for patient stratification." (PMID 39699269, 2025). "In addition, in various types of cancer, PRMT1 presence is positively correlated with neoantigens, microsatellite instability, and mutational burden of the tumor." (PMID 40001488, 2025). "Despite the therapeutic challenges in targeting it, the ongoing development of selective inhibitors and an enhanced comprehension of its actions provide PRMT1‐directed methods, particularly combination therapies, a potential new approach for addressing a wide range of malignant tumors." (PMID 41256732, 2025). "Understanding the precise mechanisms by which PRMT1 regulates metabolic pathways and redox homeostasis may open new therapeutic avenues for targeting metabolic vulnerabilities in cancer." (PMID 40801789, 2025). "This substrate sequence information was then used to develop a peptoid-based inhibitor that initiates cell death in both MDA468 and HCT116 cancer cells, which suggests PRMT1 as a viable therapeutic target and thus the development of more potent inhibitors is therefore warranted." (PMID 41301411, 2025). "This demonstrates the context ‐ dependent, dual nature of PRMT1 in cancer and indicates that universal therapeutic targeting may be ineffective." (PMID 41256732, 2025). "To determine whether PRMT1‐mediated cancer cell migration requires vimentin, we performed wound healing assays." (PMID 40884268, 2025). "In cancer cells with high PRMT1 expression, mitochondria may function as biosynthetic factories, channeling metabolic intermediates for nucleotide, amino acid, and lipid synthesis rather than oxidative phosphorylation." (PMID 40801789, 2025). "In this study, we demonstrated the important role of protein arginine methyltransferase 1 (PRMT1) in promoting chemoresistance in small cell lung cancer (SCLC) by reinforcing cancer stemness through the PRMT1-SOX2 signaling pathway, suggesting PRMT1 as a promising target for reversing stemness." (PMID 41377018, 2025). "Our discovery that PRMT1-catalyzed METTL14 arginine methylation plays a critical role in promoting ICL DNA repair gene expression reveals a new way of sensitizing cancer cells to ICL chemotherapy through targeting the METTL14 arginine methylation mediated m6A pathway." (PMID 41053315, 2025). "Scientists have already extensively studied the roles and functions of PRMT1 in cancer." (PMID 40001488, 2025). "It was reported that PRMT1 inhibition promotes ferroptosis or necroptosis in cancer cells." (PMID 39668478, 2025). "This would suggest that inactivation of FOXO1 by PRMT1 methylation in cancer cells might attenuate cancer progression." (PMID 40001488, 2025). "It has become apparent that inhibiting the function of PRMT1 will likely serve as the most beneficial therapeutic approach, since several PRMT1 inhibitors have already been shown to exert positive effects on both cancer and metabolic disease in preclinical settings." (PMID 40001488, 2025).
cancer (continued). "A combination strategy targeting both PRMT1 enzymatic activity and SWI/SNF recruitment may provide a more effective therapeutic approach for PRMT1‐driven cancers." (PMID 40270464, 2025). "PRMT1 has also been reported to regulate the activity of transcription factors involved in cancer." (PMID 40001488, 2025). "Therefore, because PRMT1 regulates FOXO activity, it is crucial to take into account the cancer type and stage when testing anti-cancer treatments by PRMT1 suppression." (PMID 40001488, 2025). "Among them, PRMT1 is overexpressed in various cancers, including HCC." (PMID 41256732, 2025). "Notably, both enzymes are implicated in chemoresistance, and targeting PRMT1 and PRMT5 has demonstrated therapeutic potential in various cancers." (PMID 40393971, 2025). "PRMT1 is widely distributed and expressed in human tissues and is highly expressed in cancer cells." (PMID 39906150, 2025). "Therefore, PRMT1 is recognized as a potential prognostic biomarker and therapeutic target in cancer." (PMID 38474197, 2024). "Studies have found that PRMT1 can regulate brain function, regulate immune system diseases, participate in glucose and lipid metabolism diseases, and affect the occurrence and development of malignant tumors." (PMID 39741976, 2024). "Additionally, in SCLC, SOX2 methylation by PRMT1, promoted its expression and molecular functions in cancer stemness, self-renewal and chemoresistance." (PMID 39703687, 2024). "In addition to its involvement in mitochondrial regulation, PRMT1 exerts effects on other cellular processes relevant to cancer." (PMID 38326807, 2024). "PRMT1 is known to be involved in the tumorigenesis of different cancer types." (PMID 38612768, 2024). "PRMT1 is an enzyme involved in the process of protein arginine methylation and play essential roles in various physiological and pathological processes, including human cancer." (PMID 39367565, 2024). "Therefore, our results suggest that PRMT1 promotes the proliferation of GSCs by activating STAT3 to upregulate the expression of cancer stemness regulators." (PMID 38474197, 2024). "Additionally, we expound on the dynamic functions of PRMT1 during distinct stages of cancer progression, elucidating its unique regulatory mechanisms within the same signaling pathway and distinguishing between its promotive and inhibitory effects." (PMID 38326807, 2024). "PRMT1 has been known as an oncogene via stimulating cancer cell proliferation or blocking apoptosis, while the opposite findings have also been reported in some experiments in which PRMT1 might inhibit proliferation and promote apoptosis in cancer." (PMID 37005412, 2023). "We then performed clone formation and MTT assays in TNBC cells before hypoxic treatment and found that the overexpression of PRMT1 could diminish the inhibition of cancer cell proliferation by downregulating circTBC1D14 expression." (PMID 36806670, 2023). "Protein arginine methyltransferase 1 (PRMT1) has been implicated in cell cycle progression, DNA repair, innate immunity, and RNA processing and proposed as a therapeutic target in several cancer types." (PMID 38201511, 2023). "Thus, PRMT1 is a potential target for cancer immunotherapy and PRMT1 inhibitor synergizes with immune checkpoint blockades to boost cancer immunity." (PMID 37193698, 2023). "In contrast, PRMT1 inhibited RIP3 to suppress cancer immune escape and tumor growth." (PMID 37005412, 2023). "In addition, various types of human cancers have been reported to exhibit PRMT1 upregulation 8,11,53,55." (PMID 37564212, 2023). "The expression of PRMT1 is consistently high in malignant tumors." (PMID 37569634, 2023). "Hence, the various roles of PRMT1 in various processes and pathological conditions, such as inflammation, oxidative stress, cancer, and lymphocyte function, have been investigated 7-12." (PMID 37564212, 2023). "Moreover, PRMT1 is an important regulator in many cellular pathways that are dysregulated in cancers." (PMID 37737256, 2023).